NPM1 (nucleophosmin 1)
Diseases named in the same sentence as NPM1 in open-access papers (continued):
Sharing a sentence is not in itself a finding about the gene and the disease.
leukemia (continued). "The SMGs identified in our mouse models included well-described melanoma and leukemia oncogenes and tumour suppressors (Muc4, Pten, Grin2a, Dnmt3a, Npm1 and Flt3) reinforcing the WES validation and the subsequent filtering of SMGs." (PMID 39223638, 2024). "Small molecule inhibitors of the menin–MLL interaction (generally referred to as menin inhibitors or MIs) have proven efficacious in reducing leukemic cell outgrowth and promoting differentiation in preclinical models of both MLLr and NPM1 mutant leukemias." (PMID 39336822, 2024). "Inhibiting menin triggers the degradation of NPM1, which leads to a reduction in the expression of genes essential for leukemia cells to grow and survive." (PMID 39428967, 2024). "NPM1::CCDC28A-expressing cells were enriched in a ckit+ granulocytic-monocytic progenitor (GMP)-like population known to contain leukemia stem cells, whereas NPM1::MLF1-expressing cells produced diverse cell types, including Gr1+ mature myeloid cells." (PMID 39443736, 2024). "Despite the promising preliminary results of early-phase clinical trials of MIs as single-agent therapies for MLLr and NPM1 mutant leukemias, some leukemias lose response to MIs alone." (PMID 39336822, 2024). "To note, the drug is currently studied in combination with other AML therapies in KMT2Ar AML, whereas its development is currently more geared towards NPM1-m leukemia as monotherapy." (PMID 39594699, 2024). "Preliminary results from these early-phase trials show promising safety and efficacy profiles associated with the use of menin inhibitors in individuals with MLLr and NPM1-mutant leukemias." (PMID 39336822, 2024). "DS has been reported with menin inhibitors with both NPM1 mutant and KMT2Ar leukemias with a similar presentation as in APL or even more pronounced." (PMID 39594699, 2024). "This was observed in a recent study outlining that patients with therapy-related NPM1-Ins AML had a long-term leukemia-free survival, similar to patients with de novo NPM1-Ins AML, whereas other secondary AML patients had decreased survival." (PMID 38791118, 2024). "DOT1L inhibitors have also been found to synergize with MI-2-2, MI-503, and VTP50469 in MLLr and NPM1 mutant leukemias, with combination treatment resulting in a more significant increase in differentiation compared to MI alone." (PMID 39336822, 2024). "In an ongoing phase I/II trial SAVE study (NCT05360160) designed for KMT2Ar, NPM1-m, and NUP98r leukemias, MRD was reported to be undetectable in three of seven treated patients (43%) with the combination." (PMID 39594699, 2024). "Given the efficacy of MIs in preclinical models, multiple MIs are currently undergoing clinical trials in MLLr and NPM1 mutant leukemias, including SNDX-5613, KO-539, JNJ-75276617, DS-1594b, BMF-219, DSP-5336, and BN104." (PMID 39336822, 2024). "In leukemia cells with nucleophosmin 1 (NPM1) mutations, FTO reduces m6A levels and enhances autophagy by upregulating the expression of TP53INP2 and promoting the LC3-ATG7 interaction, which is critical for the survival of NPM1-positive leukemia cells." (PMID 39468015, 2024). "In the context of AML cases harboring nucleophosmin 1 (NPM1) mutations 45, HOXB-AS3 assumes a regulatory role in the proliferative capacity of blasts, which are undifferentiated leukemia cells." (PMID 38213732, 2024). "Taken together, our study indicates that TP53INP2 plays an oncogenic role in maintaining the high autophagy activity of NPM1-mutated AML and provides further insight into autophagy-targeted therapy of this leukemia subtype." (PMID 36675134, 2023).
leukemia (continued). "NPM1 is one of the most prevalent mutations in AML (present in 25–35% of patients) and is reported as a definitive leukemia-founder mutation that has already been validated as an optimal and reliable MRD marker." (PMID 36900154, 2023). "Collectively, these results indicate that TP53INP2-enhanced autophagy is essential for the survival of NPM1-positive leukemia cells." (PMID 36675134, 2023). "A recent study showed that the combined mutation of NPM1/TET2/FLT3-ITD and DNMT3A observed in about 4% of NPM1-mut AMLs resulted in an aggressive leukemia phenotype." (PMID 37509445, 2023). "According to data from a retrospective study, high-dose cytarabine plus idarubicin consolidation therapy had strong anti-leukemia effects in patients with fms-like tyrosine kinase (FLT3) wild-type and mutant AML that carried an nucleophosmin 1 (NPM1) mutation." (PMID 37153795, 2023). "Intriguingly, this upregulation of HOX genes is shared with NUP98::NSD1, DEK (DEK proto-oncogene)::NUP214 (nucleoporin 214), and NPM1 (nucleophosmin 1) mutated cases, suggesting HOXA and HOXB overexpression is a common alteration in leukemia development." (PMID 37325571, 2023). "In the case of NPM1-mutated AML, we were successful in priming leukemia-specific CTLs able to kill efficiently partially HLA-matched primary myeloid leukemia blasts from all donors tested." (PMID 37345068, 2023). "The findings demonstrate that TP53INP2 is delocalized into the cytoplasm of leukemia cells by interacting with NPM1-mA." (PMID 36675134, 2023). "Menin is an essential protein that serves as a cofactor for KMT2A binding to HOX gene promoters, which results in leukemogenesis in patients with NPM1 or KMT2A rearranged leukemia." (PMID 38001669, 2023). "The increased SOCS1 level in the bone marrow of AML patients was closely associated with advanced age, mutations in FLT3-ITD, NPM1, and DNMT3A, and SOCS1 overexpression in zebrafish mimic leukemia phenotype." (PMID 38161382, 2023). "However, the role of TP53INP2 in leukemia, especially in NPM1-mutated leukemia, has been unknown." (PMID 36675134, 2023). "The cooperative mechanisms of multiple mutations (e.g., combined DNMT3A, NPM1, and FLT3 mutations) also need to be investigated to better understand the mechanisms of progression to overt leukemia." (PMID 38116120, 2023). "Categories with acute megakaryoblastic or erythroid leukemia (AMKL/AEL) phenotypes are clearly enriched in infants, whereas CBF leukemias and mutation-defining leukemias (e.g., UBTF, NPM1, CEBPA) were enriched in adolescents and young adults." (PMID 37398194, 2023). "Menin inhibitors also appear to lead to decreased expression of HOXa/b targets, including MEIS1, and lead to differentiation in NPM1/DNMT3a mutant knock-in mice and leukemia cell lines." (PMID 36497385, 2022). "Of note, high expression level of NPM1 has been described as an early marker of proliferative activity in leukemia-derived cell lines, as it precedes the S-phase of the cell cycle." (PMID 36282861, 2022). "R1 splice variant is well studied, the biological significance of other NPM1 transcripts and their contribution to leukemia maintenance and progression remains largely unexplored." (PMID 36282861, 2022). "NPM1-mutated CAR-T cells showed efficient and specific anti-leukemia activity against NPM1c+HLA-A2+ leukemia cells and primary AML blasts." (PMID 36237321, 2022). "The combination of menin and FLT3 inhibitors significantly reduced leukemia burden and induced the long-term remissions in a PDX model with both NPM1 and FLT3-ITD mutations." (PMID 36237321, 2022). "Oncomine database analysis showed that the expression of NPM1 in colorectal cancer, head-neck cancer, kidney cancer, leukemia, liver cancer, lung cancer, lymphoma and sarcoma was higher than that in normal tissues." (PMID 34335635, 2021). "MI-3454 induced complete remission or regression of leukemia in a mouse xenograft model of MLL1 translocation or NPM1 mutant leukemia derived from AML patients." (PMID 34201935, 2021).
leukemia (continued). "Our data herein demonstrated the high level of lncRNA HOTAIRM1 in NPM1-mutated leukemia cells and indicated that HOTAIRM1 was upregulated at least partially by mutant NPM1 via KLF5-dependent transcriptional regulation." (PMID 34615546, 2021). "FLT3-ITD with additional NPM1 mutation, AML1-ETO fusion gene, NUP98 fusion, CBFβ-SMMHC fusion gene, and TET2 deletion can cause leukemia." (PMID 33836835, 2021). "Here, we present 6 challenging NPM1-mutated AML cases, in order to provide criteria for the appropriate diagnosis and therapy of this common leukaemia entity." (PMID 33879827, 2021). "Here, we provide examples of instructive cases of NPM1-mutated AML, in order to provide criteria for the appropriate diagnosis and therapy of this frequent leukaemia entity." (PMID 33879827, 2021). "Another study has discovered cooperation of NPM1 and IDH2 mutations for leukemia development in mice through activation of the Hoxa9/Meis1 pathway, where NPMc and IDH2/R140Q increase the expression of Hoxa9 and Meis1, respectively." (PMID 34944812, 2021). "For instance, the NPM1 mutation was reported to be correlated with over-expression of PBX3 and HOXA gene cluster, which is required for the maintenance of leukemia cells harboring NPM1 mutation." (PMID 34051812, 2021). "On one hand, rRNA 2′Ome are required for normal hematopoiesis and bone marrow functions, and the variability of 2′Ome at these positions is observed in NPM1-related leukemia or DC and contributes to the disease’s phenotypes." (PMID 34440717, 2021). "These leukemias were highly enriched in NPM1, and particularly in composed NPM1/DNMT3A mutants, but NPM1 status alone was insufficient to explain the existence of the FLT3-like pattern." (PMID 33592069, 2021). "Here, the authors show that mutant NPM1 activates a HOXB locus-associated long non-coding RNA which is essential for its associated oncogenic transcriptional program and leukaemia development." (PMID 33782403, 2021). "Among the metabolic genes downregulated in NPM1/cohesin-mut compared with NPM1-mut AML, CHST13, ADCY9, PRR16, LPL, and SLC1A3 were confirmed by STAG2-deficient model of NPM1-mut leukemia." (PMID 34193978, 2021). "The co-occurrence of mutations in DNMT3A, NPM1 and FLT3-ITD is the most frequent combination of mutations found in AML, which highlights the synergy of this complex gene interaction in causing leukemia." (PMID 32545659, 2020). "Apart from the NUP98 fusions, Hox gene dysregulation has also been associated with MLL fusions, the CALM-AF10 fusion, and NPM1 and IDH1 mutations in leukemia." (PMID 32993115, 2020). "This NUP98-NSD1-positive PDX model was analyzed in the 6th transplantation and showed AML with normal karyotype, while it was wildtype for genes frequently mutated in leukemia, such as FLT3, NRAS, NPM1, IDH1/2, and DNMT3A." (PMID 32993115, 2020). "Our previous experimental data showed that NPM1 mutant promoted migration and invasion of leukemia cells through matrix metalloproteases (MMPs) up-regulation." (PMID 31777586, 2019). "We found that a high PD-L1 expression on leukemia blasts predicts for worse overall survival (OS), specifically in patients with internal tandem duplications in FLT3 (FLT3-ITD) and with mutated NPM1." (PMID 31185600, 2019). "Functional evaluations showed that silencing VCAN by shRNA significantly suppressed cell migration and invasion capacity, whereas increased VCAN by overexpressing NPM1-mA enhanced migration and invasion ability of leukemia cells." (PMID 31777586, 2019). "All three NPM1 transcripts were proportionally upregulated in both types of leukemia compared to control samples." (PMID 30126426, 2018). "Analysis of ddPCR results revealed the evident differences in the levels of the particular NPM1 transcripts in all samples, either leukemia or HV." (PMID 30126426, 2018).
leukemia (continued). "The levels of the particular NPM1 transcripts were significantly different but highly correlated with each other in both leukemia and control samples." (PMID 30126426, 2018). "Herein, we report that INPP4B is frequently upregulated in NPM1-mutated AML, and promotes leukemia cell survival in a SGK3-dependent and AKT-independent manner." (PMID 29343273, 2018). "We previously determined that the ERK activation was continuously increased by NPM1-mA in leukemia cells." (PMID 29343273, 2018). "Decreasing FOXM1 activity in human and murine leukemia cells with WT NPM1 led to decreased clonogenicity and increased apoptosis." (PMID 30089730, 2018). "Given that NPM1-mA enhanced INPP4B expression, we then validated the impact of NPM1-mA on the proliferation of leukemia cells." (PMID 29343273, 2018). "After dividing the leukemia samples into AML and ALL, we noted similar levels of all NPM1 transcripts in both types of leukemia." (PMID 30126426, 2018). "The results revealed that enforced NPM1-mA expression in leukemia cells (THP-1 and HL60) increased miR-10b expression, whereas silenced NPM1-mA expression in OCI-AML3 cells decreased miR-10b levels." (PMID 27669739, 2016). "Here, we demonstrated that NPM1-mA inhibited myeloid differentiation of leukemia cells in vitro, and that the miR-10b/KLF4 axis was involved in this process." (PMID 27669739, 2016). "Here, we showed that enforced expression of NPM1 mutation type A (NPM1-mA) inhibits myeloid differentiation of leukemia cells, whereas knockdown of NPM1-mA has the opposite effect." (PMID 27669739, 2016). "For young adults (age < 60 years) and fit elderly patients (especially those harboring NPM1 mutations and CBF leukemia) the intensive anthracycline and cytarabine regimen, “7 + 3”, induction therapy is the standard of care." (PMID 26959069, 2016). "Screening of leukemia-initiating mutations, such as DNMT3A, NPM1 or IDH1/2 mutations should be performed at diagnosis but only NPM1 and IDH1/2 are robust target for MRD monitoring." (PMID 26486081, 2015). "This putative normal HSC, CD34+CD38– ALDHbright, cell population of 7 of these 19 CD34-positive AML cases was essentially devoid of cells with the leukemia-specific cytogenetic abnormalities FLT3-ITD and/or mutated NPM1." (PMID 24244383, 2013). "Moreover, in NPM1‐mutated AML models, this molecule prevented disease progression by targeting pre‐leukemic clones and was also effective in treating established leukemia." (PMID 39887730, 2026). "Moreover, non‐rearranged KMT2A‐complexes have been demonstrated to be crucial for disease development and maintenance in NPM1‐mutated and NUP98‐rearranged leukemia, expanding the spectrum of genetic disease subtypes that are dependent on KMT2A." (PMID 39887730, 2026). "Even though being approved by the FDA as a highly effective treatment option for patients with relapsed or refractory leukemia with KMT2A‐rearrangements or NPM1‐mutations, roughly 50% of patients show no clinical response." (PMID 40181550, 2026). "Mutated NPM1 is a promising and potential target for NPM1-mutated AML because the NPM1-mutated protein does not exist in normal tissues, and therefore, it is an ideal leukemia-specific antigen (LSA)." (PMID 40557158, 2025). "A prior study in NPM1 mutant leukemia models also showed sensitivity to SINE compounds, while the treatment prolonged survival by approximately 24–25 days, but could not eradicate the disease." (PMID 40148556, 2025). "Lenalidomide could be used as a potential treatment for NPM1-mutated AML, especially when combined with checkpoint inhibitors to improve leukemia-associated antigen-specific response." (PMID 40647396, 2025).
leukemia (continued). "Categories with acute megakaryoblastic leukemia (AMKL) or acute erythroid leukemia (AEL) phenotypes are clearly enriched in infants, whereas CBF leukemias and mutation-defined leukemias (for example, UBTF, NPM1, CEBPA) were enriched in adolescents and young adults." (PMID 38212634, 2024). "Specific genetic aberrations, such as RUNX1::RUNX1T1, CBFB::MYH11, and nucleophosmin 1 (NPM1) mutations, constitute markers of MRD but about 40% of children with AML harbor leukemia-specific targets, which makes these genetic targets clinically applicable in only minor fraction of children." (PMID 38720804, 2024). "Importantly, five out of six mice transplanted with NPM1::CCDC28A-expressing cells and two out of twelve mice transplanted with NPM1::MLF1-expressing cells developed leukemia within 6 months after transplantation." (PMID 39443736, 2024). "Many studies have demonstrated the involvement of NPM1 in many disease types, including leukemia and solid tumors, suggesting that NPM1 may have a role in the course of disease." (PMID 38662949, 2024). "Therefore, disrupting the menin‐KMT2A axis is a promising treatment approach for tackling leukemias driven by KMT2A rearrangements and NPM1 mutations." (PMID 39428967, 2024). "Interestingly, menin inhibition in WT-MLL AML, as with NPM1-m leukemia, has also been effective in early-phase studies." (PMID 39594699, 2024). "In addition to its oncogenic activity in KMT2Ar and NPM1-m leukemia, it can also directly interact with histones and read nucleosomal methylated H3K79me2." (PMID 39594699, 2024). "Gene editing studies have shown that NPM1 mutant leukemias are dependent on menin and MEIS1 for their leukemogenic function, and knocking out these genes disrupts the menin-HOX-MEIS1 axis that leads to differentiation, loss of proliferation, and impaired leukemogenesis." (PMID 39594699, 2024). "In addition to venetoclax and MIs, FLT3 inhibitors have also exhibited synergy with MIs in MLLr and NPM1 mutant leukemias." (PMID 39336822, 2024). "Overall, there are multiple promising combinatorial approaches that may combat MI resistance and improve the response of MLLr and NPM1 mutant leukemias to MIs." (PMID 39336822, 2024). "NPM1 is another protein that is important in the development of leukemia." (PMID 39428967, 2024). "Besides, in AML with mutated NPM1, the KMT2A-menin synergy prompts HOX and MEIS1-mediated transcription of leukemia associated genes." (PMID 37816719, 2023). "Our data suggested that the AML tipping point signatures, including Npm1 and Phdgh, might be a critical driver for leukemia initiation at the tipping point." (PMID 37130348, 2023). "Therefore, we performed further functional studies of Npm1 to verify its effect on the development of leukemia." (PMID 37130348, 2023). "Despite these existing studies, the underlying mechanism for autophagic activation has not been fully elucidated in NPM1-mutated leukemia." (PMID 36675134, 2023). "The results showed that there is higher TP53INP2 expression in OCI-AML3 cells with NPM1 mutation type A(NPM1-mA) compared to other leukemia cell lines without NPM1-mA." (PMID 36675134, 2023). "In this specific patient, the emergence of a cellular immune response to wt-NPM1 was not accompanied by side effects, such as GVHD or BM aplasia, and coincided with leukemia control, further suggesting the potential role and relative safety of NPM1-directed immunity after HSCT." (PMID 37345068, 2023). "The exclusivity of NPM1 and RUNX1 mutation in AML might suggest that RUNX1 mutation shares a similar role with NPM1 mutations in leukaemia development." (PMID 37188777, 2023). "Interestingly, the results from our experiments revealed that NPM1-mA reduces the global m6A abundance by upregulating FTO expression, suggesting the possible link between NPM1-mA and the aberrant m6A modification in leukemia." (PMID 35211409, 2022).